LINC01050 (long independently transcribed non-coding RNA 1050)
Gene: Long non-coding RNA gene on chromosome 13 (42,810,348 to 42,819,861, reverse strand). Ensembl gene ENSG00000271216.
Diseases named in the same sentence as LINC01050 in open-access papers:
LINC01050 is named in the same sentence as 3 diseases in open-access papers, as found by Europe PMC text mining. Sharing a sentence is not in itself a finding about the gene and the disease. The quoted sentences say what the papers report.
gastric cancer (2 papers, 2021 to 2022). A primary or metastatic malignant neoplasm involving the stomach. "c-Myc can bind to the LINC01050 promoter to improve transcription of LINC01050 and enhances metastasis of gastric cancer cells." (PMID 36230902, 2022). "The expression of LINC01050 in the context of gastric cancer was assessed using The Cancer Genome Atlas datasets." (PMID 34749766, 2021). "LINC01050 was significantly up-regulated in gastric cancer, and its high expression was positively correlated with a poor prognosis." (PMID 34749766, 2021). "Furthermore, overexpression of LINC01050 was confirmed to promote gastric cancer cell proliferation, migration, invasion, and epithelial-mesenchymal transition in vitro and tumor growth in vivo." (PMID 34749766, 2021). "LINC01050 may be considered a potential therapeutic target for gastric cancer." (PMID 34749766, 2021). "Moreover, mechanistic investigations revealed that LINC01050 functions as a molecular sponge to absorb cytosolic miR-7161-3p, which reduces the miR-7161-3p-mediated translational repression of SPZ1, thus contributing to gastric cancer progression." (PMID 34749766, 2021).
cancer (1 paper, 2021). A tumor composed of atypical neoplastic, often pleomorphic cells that invade other tissues. "To date, the biological function and expression pattern of LINC01050 in cancer have not been unraveled." (PMID 34749766, 2021).
tumor (1 paper, 2021). "Ki67 and PCNA staining of the subcutaneous tumor further confirmed that the ectopic expression of LINC01050 promoted GC cell proliferation in vivo." (PMID 34749766, 2021). "We found that LINC01050 was significantly up-regulated in GC tissues compared with the corresponding non-tumor tissues, and its expression may serve as a potential independent predictor for overall survival in GC." (PMID 34749766, 2021). "Moreover, a tumorigenesis study in nude mice revealed that overexpression of LINC01050 promoted tumor growth." (PMID 34749766, 2021). "Furthermore, LINC01050 overexpression promoted GC cell proliferation, migration, invasion, and EMT in vitro and tumor growth in vivo." (PMID 34749766, 2021).